RN7SKP10 (RN7SK pseudogene 10)
Gene: Miscellaneous RNA gene on chromosome 13 (109,915,096 to 109,915,420, forward strand). Ensembl gene ENSG00000201161.
Homologues: Orthologues: chimpanzee 7SK (94% identical). Paralogues in human: 7SK (74% identical), RN7SKP203 (73% identical), RN7SKP47 (71% identical), RN7SKP9 (71% identical), RN7SKP176 (71% identical), RN7SKP255 (71% identical), RN7SKP79 (71% identical), RN7SKP180 (70% identical), RN7SKP189 (70% identical), RN7SKP211 (70% identical), RN7SKP37 (70% identical), RN7SKP124 (70% identical), and 285 more.